ESR2 (estrogen receptor 2)
Diseases named in the same sentence as ESR2 in open-access papers (continued):
Sharing a sentence is not in itself a finding about the gene and the disease.
prostate carcinoma (188 papers, 2004 to 2025). A carcinoma that arises from epithelial cells of the prostate gland. "The prevalence of ESR1 (which encodes ERα) and ESR2 (which encodes ERβ) mutations was 3% (5/150) in individuals with metastatic or advanced PCa, whereas it was 2% (11/492) in patients with early prostate cancer, according to a genomic dataset." (PMID 36979805, 2023). "The case control study, which included 510 prostate cancer patients, concluded that the polymorphism rs3020449 in the ESR2 gene should be considered as a risk factor for prostate cancer in Slovak males." (PMID 35087479, 2021). "We pooled the data of 7 studies containing 9634 cases and 10803 controls to clarify the association of ESR2 rs4986938 and prostate cancer." (PMID 31523634, 2019). "In the meta-analysis of GWAS, we identified two novel loci associated with prostate cancer, rs58262369 at 14q23.2 (ESR2) and rs12791447 at 11p15.4 (PPFIBP2)." (PMID 26443449, 2015). "On the other hand thus far, no inherited variations in AR, estrogen receptor-1 (ESR1), or estrogen receptor-2 (ESR2) genes have been found associated with prostate cancer aggressiveness or with the efficacy of androgen deprivation in Caucasian populations." (PMID 22956944, 2012). "A nested case-control study was conducted to examine the associations between selective polymorphisms of ESR 1, ESR2 genes and the risk of developing prostate cancer in a community-based cohort in Washington County, Maryland." (PMID 19654868, 2009). "The association between genetic polymorphisms of estrogen receptors α (ESR1) and β (ESR2) and prostate cancer risk was examined in a nested case-control study in Washington County, Maryland." (PMID 19654868, 2009). "Genetic polymorphisms of the ESR1 and ESR2 have been reported to be associated with prostate cancer risk." (PMID 19654868, 2009). "Four previous studies have been published regarding association between polymorphisms in ESR2 and prostate cancer risk." (PMID 19654868, 2009). "Of recent, two studies have reported null association between ESR2 CA repeat polymorphism and prostate cancer." (PMID 19654868, 2009). "Even for the same SNP (e.g. ESR2 rs1256049), its association with prostate cancer susceptibility may exhibit opposite effects across different ethnic populations." (PMID 39882449, 2024). "However, an interactive association with BMI was observed in the relationship between prostate cancer risk and genotypes of ESR2 38 bp 3′ of STP G>A (rs4986938) (p = 0.031)." (PMID 19654868, 2009). "Recent studies further found that ATBF1 inhibited prostate cancer cell proliferation via cooperation with ESR2 to regulate the transcription of MYC." (PMID 36476423, 2022). "Higher levels of ATBF1 and estrogen receptor 2 (ESR2) in prostate cancer tissue samples were correlated with better patient survival." (PMID 36476423, 2022). "Another example would be estrogen receptors (ESR1 and ESR2), against which 5 drugs were developed to cure breast and prostate cancers." (PMID 31803618, 2019). "A 48-hour incubation with this heptapeptide resulted in significantly decreased expression of ESR1 and a noticeable increase in the mRNA level of ESR2 in prostate cancer cells." (PMID 30361641, 2018). "Our findings indicate that Ang1–7 reduced the expression of ESR1 and increased that of ESR2 in prostate cancer cells." (PMID 30361641, 2018). "It has been found previously that ESR2 is highly expressed in prostate cancer lines, while ESR1 is expressed in less extend." (PMID 30361641, 2018). "In order to show the effect of ESR1 and ESR2 promoter methylation and demethylation on gene expression, prostate cancer cell lines LNCaP, DU145 and PC3 were treated with 5-aza-2′-deoxycytidine (AZA)." (PMID 29731970, 2018). "Estrogen receptor β (ERβ, also known as ESR2) has been shown to have a role as a tumor suppressor in prostate cancer in various reports." (PMID 28380417, 2017).
prostate carcinoma (continued). "In contrast, expression of the main isoform of estrogen receptor β (ERβ/ESR2), ERβ1, is reduced during prostate cancer progression." (PMID 26010887, 2015). "We identify two independent susceptibility loci for prostate cancer at 11p15.4 (rs12791447, P=3.59 × 10−8; PPFIBP2) and 14q23.2 (rs58262369, P=6.05 × 10−10; ESR2)." (PMID 26443449, 2015). "Only 3 out of 10 selected SNPs (ESR1 Ex1+392T>C, ESR2 Ex8+229G>A, and ESR1 Ex4-122C>G) were studied in the past, where null associations with prostate cancer risk were observed, consistent with our study findings." (PMID 19654868, 2009). "Among those who were diagnosed with advanced prostate cancer, associations between prostate cancer risk and genotypes were suggestive for four SNPs: ESR1 Ex1+392T>C, ESR1 IVS6+52G>T, ESR2 38 bp 3′ of STP G>A and ESR2 5659 bp 3′ of STP A>G." (PMID 19654868, 2009). "An interaction association by BMI on the relationship between prostate cancer risk and ESR genotypes was suggested for ESR2 38 bp 3′ of STP G>A (P = 0.031)." (PMID 19654868, 2009). "In particular, for men with G/A, G/G genotype in ESR2 38 bp 3′ of STP G>A, having a BMI of ≥30 kg/m2 was associated with a reduced the odds of developing prostate cancer by 57% compared to having a BMI of <25 kg/m2 (p-value for trend = 0.01)." (PMID 19654868, 2009). "In all evaluated prostate cancer cell lines, we found a significant increase of expression of ESR2 (* p < 0.05, ** p < 0.01) after co-exposure to 5 μM DON and 100 nM DHEA, while for the PNT1A cells the effect was opposite and the expression was significantly decreased (*** p < 0.001)." (PMID 34678978, 2021). "Furthermore, decreased expression of ESR1 and a noticeable increase in ESR2 mRNA was observed in all prostate cancer cells." (PMID 32872192, 2020). "Firstly, we examined the significance of three hormone receptors: AR, ESR1, ESR2 in the biology of prostate cancer regarding the effect of their expression on tumor recurrence according to patient’s age (four age groups: ≤50, 51–60, 61–70, 70> years old) through disease-free survival (DFS) analysis." (PMID 29206234, 2017). "Especially, the role of ESR2 is believed to be important in prostate cancer progression." (PMID 29206234, 2017). "In men with a T/T genotype in ESR1 Ex1+392T>C, A/A genotype in ESR1 Ex8+229G>A, and A/G or G/G genotype in ESR2 5696 bp 3′ of STP A>G, high phytoestrogen group had a 58% (P = 0.048), 64% (P = 0.047) and 80% (P = 0.034) lower risk of developing prostate cancer, respectively." (PMID 19654868, 2009). "Other studies have consistently found that ESR2 is expressed in metastatic prostate cancer cells." (PMID 19654868, 2009). "Swedish study has identified rs2987983 in the promoter region of ESR2, which was not included in our study, as a potential effect modifier in the relationship between the intake of phytoestrogen and the risk of prostate cancer." (PMID 19654868, 2009). "Exploratory analyses examined how the ESR1 and ESR2 SNPs of interest modified the association between BMI/phytoestrogen and prostate cancer risk and also how BMI and phytoestrogen altered the association between the ESR1 and ESR2 SNPs of interest and prostate cancer risk." (PMID 19654868, 2009). "It is worth emphasizing that estrogen receptor 2 (ESR2/ERβ) was highly expressed, while estrogen receptor 1 (ESR1/ERα) had a relatively low level of expression or was almost undetectable in prostate cancer lines." (PMID 30361641, 2018). "Oestrogen plays a vital role in mammary gland development and is also involved in prostate cancer progression, exerting its biological actions through the oestrogen receptors ESR1 and ESR2 (refs 8, 9)." (PMID 26443449, 2015). "Among these six, HLF, JUN, c-MYC, EGR1, SMAD1, and HIF1A, were also identified as PTEN-controlled TFs, and four, ESR2, MYB, RELA, and USF1, as prostate cancer-related TFs." (PMID 22347425, 2012).
prostate carcinoma (continued). "Previous studies from our laboratory have already shown that, in androgen-independent prostate cancer cells PC-3 and DU-145, estrogen receptors (ER) ERα (ESR1) and ERβ (ESR2) are mostly located outside the nucleus of these cells, indicating the activation of rapid signaling pathways." (PMID 33503805, 2021). "Nicotinamide phosphoribosyltransferase (NAMPT), in our experiments more than 4-fold upregulated after ESR2 knockdown in HEC-1A cells, is overexpressed in several cancer entities such as ovarian, breast, gastric, colorectal, and prostate cancer, gliomas and B-cell lymphomas." (PMID 31357971, 2019). "GATA2, 3-fold overexpressed after ESR2 knockdown in HEC-1A cells, is a transcription factor, which has been reported to be overexpressed in non-familial EVI1-positive acute myeloid leukemia as well as in prostate cancer." (PMID 31357971, 2019). "Genes involved in the signal transduction above are all target genes of highly expressed miRNAs in prostate cancer samples; therefore, the expression of ESR1 and ESR2 will be down-regulated which is in accordance with the previous report by Gamba and his co-authors." (PMID 24555436, 2013). "In this study, there was no overall association between prostate cancer risk and genotypic and allelic frequencies of ESR1 and ESR2 SNPs." (PMID 19654868, 2009). "For ESR2, A allele in 38 bp 3′ of STP G>A and A allele in 5659 bp 3′ of STP A>G were associated with an increased risk of advanced prostate cancer but association were not statistically significant." (PMID 19654868, 2009). "In summary, no overall statistically significant association between prostate cancer risk and the selected ten SNPs in ESR1 and ESR2 genes was observed." (PMID 19654868, 2009). "In addition, the remaining altered genes that are not depicted in the KEGG Pathway schematic, including ESR2 (−5.26, p = 0.013) and CDH1 (−2.08, p = 0.019), are implicated in prostate cancer progression." (PMID 25799167, 2015).
endometriosis (157 papers, 2010 to 2026). The growth of functional endometrial tissue in anatomic sites outside the uterine body. "Dysregulation of the ESR2/ESR1 ratio in ectopic endometrial stromal cells has been implicated in endometriosis pathogenesis and disease severity." (PMID 40072055, 2025). "When established, endometriosis lesions are characterized by estrogen dominance caused by the local estrogen production and altered ER signaling, presenting an overexpression of ESR2 and a downregulation of ESR1." (PMID 39200122, 2024). "Increased ESR2 has been linked to increased proliferation, apoptosis, inflammation, and pain transmission in endometriosis." (PMID 37996888, 2023). "Such overexpression of ERβ in endometriosis has been linked to significantly pathologically reduced methylation of a CpG island in the promoter region of the ERβ gene (ESR2)." (PMID 37569571, 2023). "The aberrations in methylation status within these regions were previously associated with changes in ESR1 and ESR2 transcriptional activity in estrogen-dependent cancers and endometriosis." (PMID 35682668, 2022). "Such overexpression of ERβ in endometriosis was associated with abnormally lowered methylation of a CpG island in the promoter region of the ERβ gene (ESR2)." (PMID 35935991, 2022). "The results obtained during the analysis indicate that the polymorphisms rs4986938 and rs928554 of the ESR2 gene are associated with the occurrence of endometriosis." (PMID 34638893, 2021). "A correlation was also identified in the Chinese women between rs17179740 A/G polymorphism of the ESR2 gene and endometriosis." (PMID 33153202, 2020). "A team of Japanese researchers demonstrated that the specific polymorphism, which is observed in ESR2 gene, is associated with the higher incidence of endometriosis in stage IV." (PMID 33153202, 2020). "The rs4986938 polymorphism of the ESR2 gene was also associated with advanced endometriosis observed in the Japanese population." (PMID 33153202, 2020). "Disorders in the level of ESR2 gene expression, observed in endometriosis as related to the types and sites of lesions associated with the disease, are confirmed by world literature reports." (PMID 33153202, 2020). "They concluded that the increased expression of ESR2 in endometriosis is caused by DNA hypomethylation of the promoter region (from − 163 to − 48) of ESR2." (PMID 30728052, 2019). "Microsatellites ESR1_TA and ESR2_CA in the ESR1 and ESR2 genes, respectively, have also been reported to be associated with other diseases such as bone mineral density, osteoarthritis, and endometriosis." (PMID 22792352, 2012). "ESR2 polymorphism has been reported to play a role in endometriosis in various populations such as Brazilian and Japanese women." (PMID 22203846, 2011). "Therefore, the PCB126/AXL/GAS6/ESR2 axis represents a key mechanism underlying the induction of endometriosis-associated DNA methylation via DNMT3A." (PMID 41054802, 2025). "Importantly, the authors of this case-control study (n = 79) within 24 months of the recruiting period noted that the ERβ gene ESR2 RsaI polymorphism significantly modified these effects of genistein for advanced endometriosis." (PMID 37569571, 2023). "Due to the small amount of research on the analysis of CYP19A1 and ESR2 gene expression and polymorphisms in patients with endometriosis, the research makes a significant contribution to expanding the knowledge about the impact of genetic factors on the development of endometriosis." (PMID 34638893, 2021). "The ERβ receptor encoded by the ESR2 gene is the dominant isoform in those with endometriosis." (PMID 34638893, 2021). "The ERβ receptor, encoded by the ESR2 gene, is a dominating isoform in patients with endometriosis." (PMID 33153202, 2020). "In the meantime, ESR2 also exhibited high expression and studies had proved that ESR2 could influence susceptibility to endometriosis with infertility." (PMID 33490107, 2020).
endometriosis (continued). "Thus, E2 appears to directly cause an increased inflammatory response through ESR2 in addition to enhancing endometriotic cell proliferation in endometriosis." (PMID 31387263, 2019). "The screening for increased ESR2 expression could offer a diagnostic tool to identify women at risk of developing endometriosis." (PMID 22203846, 2011). "The disruption of ESR2 and the ensuing decrease of the ESR1/ESR2 ratio could be the culprit for the cascade of molecular events that initiates cellular deregulation and tissue remodeling associated with endometriosis." (PMID 22203846, 2011). "Higher levels of ESR1 (estrogen receptor 1) and ESR2 (estrogen receptor 2) in diabetic endometriosis tissues suggest a potential link between metabolic disturbances and hormonal signaling in disease progression." (PMID 40649777, 2025). "Collectively, our study demonstrated that exposure to PCB126 indirectly upregulated Dnmt3a through the activation of the AXL/GAS6/ESR2 axis, leading to dysregulation of epigenomic regulation in the endometrium and promoting the progression of endometriosis." (PMID 41054802, 2025). "ESR1 and ESR2 expression is upregulated in the eutopic and ectopic endometrium from endometriosis patients compared to control endometrium, with ectopic lesions showing higher expression of both genes compared to eutopic tissue." (PMID 40072055, 2025). "The SRC-1 isoform/MMP-9/ESR2 axis has been identified as a key driver of endometriosis by inhibiting apoptosis and promoting inflammatory responses within endometriotic lesions." (PMID 41054802, 2025). "Our findings establish a mechanistic connection between environmental PCB126 exposure and endometriosis progression via the AXL/ESR2/DNMT3A axis." (PMID 41054802, 2025). "The ability of PCB126 to enhance ESR2 activity and stimulate endometriosis lesion growth via AXL represents a unique estrogen mimicry mechanism by which persistent organic pollutants promote estrogen-sensitive pathologies." (PMID 41054802, 2025). "Several studies have shown that ESR2 mRNA levels are higher in endometriosis compared to normal endometrium." (PMID 40792071, 2025). "Endometriosis is an estrogen-dependent disease, with both ESR2 and ESR1 playing critical roles in its progression." (PMID 41054802, 2025). "This aberrantly low ESR1:ESR2 ratio changes the mode of action of estrogen and influences diverse pathological processes in endometriosis, including apoptosis, proliferation, invasiveness, and inflammation." (PMID 38549776, 2024). "Another estrogen receptor, ESR2, is upregulated in women with endometriosis and has been shown to drive the pathogenesis of endometriosis via modulating apoptosis complexes and the inflammasome in the transgenic mouse model." (PMID 39684860, 2024). "In humans, studies on CREB1 and ESR2 showed that they indirectly promoted the development of endometriosis." (PMID 37947633, 2023). "These disorders have been linked to abnormally lowered methylation of a CpG island in the promoter region of the ERβ gene (ESR2) in endometriosis, resulting in ERβ overexpression." (PMID 33411206, 2021). "Literature data indicate that studies draw attention to the significant role of estrogen receptor genes, especially the ESR2 gene and the CYP19A1 gene for the susceptibility and occurrence of endometriosis." (PMID 34638893, 2021). "Recent studies have shown that the polymorphisms rs17179740 of the ESR2 gene and rs2899470 of the CYP19A1 gene are associated with the occurrence of endometriosis." (PMID 34638893, 2021). "Literature data indicate the particular role of estrogen receptor genes, especially of the ESR2 gene and of the CYP19A1 gene for the susceptibility to and the incidence of endometriosis." (PMID 33153202, 2020). "ESR2 mRNA levels were found to be 34-fold higher in endometriosis compared with the normal endometrium." (PMID 32316608, 2020).